FGF2 (fibroblast growth factor 2)
Diseases named in the same sentence as FGF2 in open-access papers (continued):
Sharing a sentence is not in itself a finding about the gene and the disease.
fibrosarcoma (16 papers, 2010 to 2025). A malignant mesenchymal fibroblastic neoplasm affecting the soft tissue and bone. "The inflammation-associated long pentraxin 3 (PTX3) was found to reduce FGF-2-mediated angiogenesis, but its role on fibrosarcoma immune inflammatory infiltrate is still unknown." (PMID 31533326, 2019). "In fibrosarcoma, cancer cells and their surrounding immune inflammatory cells overexpress or induce FGF2 expression, which plays a key role in tumor progression and angiogenesis." (PMID 33381388, 2020). "Again, neither VEGF blockade nor imatinib monotherapy produced any significant antitumor activity in FGF-2+ fibrosarcomas, indicating that FGF-2 significantly contributes to development of drug resistance through a compensatory mechanism." (PMID 32709869, 2020). "The proangiogenic, pleiotropic FGF-2 is synthesized by normal dermal fibroblasts and at all the stages of development of a transgenic mouse model of fibrosarcoma, its expression being correlated to angiogenesis and tumor progression." (PMID 31533326, 2019). "Fibrosarcoma cells and its surrounding immune inflammatory infiltrates overexpress or induce the expression of fibroblast growth factor-2 (FGF-2) that have a crucial role in tumor progression and angiogenesis." (PMID 31533326, 2019). "To further validate our findings, we used the T241 fibrosarcoma model to genetically express a secretory form of the human Fgf2 gene." (PMID 29423271, 2018). "This is also the case in fibrosarcoma cells, as FGF-2 stimulates in a cell-specific manner the migration capability of fibrosarcoma cells by decreasing HYAL-2 expression in HT1080 cells and by increasing HAS1 and -2 expressions." (PMID 24083250, 2013). "Consequently, reduction of tumor vessel density and blood perfusion by combination therapy led to significant increases of tumor hypoxia, which would be otherwise insensitive to anti-VEGF and imatinib monotherapy in FGF-2+ fibrosarcomas." (PMID 32709869, 2020). "Moreover, the forced expression of FGF2/Platelet-derived growth factor-BB in fibrosarcoma cells increases their aggressiveness, thus promoting neovascularization and a higher metastatic potential." (PMID 30443492, 2018). "Accordingly, human HT-1080 and murine MC17-51 fibrosarcoma cells express FGF2 and different FGFRs." (PMID 30443492, 2018). "On these bases, given its role on fibroblast transformation and its impact on tumor vascularization, the FGF2/FGFR system might represent a promising target for fibrosarcoma therapy." (PMID 30443492, 2018). "Indeed, in a transgenic murine model of dermal fibrosarcoma, FGF2 is actively produced by fibroblasts at all stages along their malignant transformation (mild fibromatosis, aggressive fibromatosis, and fibrosarcoma) and its expression correlates with the angiogenic phenotype of the tumor." (PMID 30443492, 2018). "To study the functional impact of FGF-2 on vascular pericytes in TME, we measured the proliferative population of pericytes in the T241 fibrosarcoma model in vivo." (PMID 29423271, 2018). "Growth factors, including PDGF-BB, TGFβ2, and FGF-2, enhanced hyaluronan deposition to ECM and modulated HA-receptor expression in fibrosarcoma cells." (PMID 24083250, 2013). "Fibroblast growth factor-2 (FGF2) and its tyrosine-kinase receptors (FGFRs) play pivotal roles in fibrosarcoma onset and progression, FGF2 being actively produced by fibroblasts in all stages along their malignant transformation to the fibrosarcoma stage." (PMID 30443492, 2018).
Hypertension (16 papers, 2013 to 2026). The presence of chronic increased pressure in the systemic arterial system. "We found a significant association between FGF-2 concentration and hypertension, with lower levels observed in hypertensive patients." (PMID 40943671, 2025). "By contrast, genetic variants in FGF2 also showed an association with hypertension." (PMID 35980984, 2022). "Interestingly, all of the SNPs in FGF2 that were associated with hypertension suggested that the risk of hypertension was diminished with minor alleles." (PMID 35980984, 2022). "While FGF-2 overproduction has been reported in pulmonary hypertension, its role in neurogenic blood pressure regulation and hypertension-induced renal injury is well established." (PMID 40943671, 2025). "In diabetic patients, the observed lower concentrations of FGF-2 and FGF-22 could indicate a significant association with hypertension, emphasizing the interconnected nature of these metabolic conditions." (PMID 40943671, 2025). "It has been shown that FGF2 plays positive pathophysiological roles in tissue remodeling, bone health, and regeneration, such as the repair of neuronal damage, skin wound healing, joint protection, and the control of hypertension." (PMID 34203430, 2021). "Statistical analysis revealed a significant relationship between FGF-2 and FGF-22 concentrations and hypertension (p = 0.03; p = 0.01)." (PMID 40943671, 2025). "The statistical analysis revealed statistically significant differences in median FGF-2 concentrations between patients with and without hypertension (p = 0.03), with lower median levels observed in patients with hypertension." (PMID 40943671, 2025).
Myocardial fibrosis (16 papers, 2013 to 2026). "However, the effect and underlying mechanism of the combined use of CHIR99021 and FGF2 on myocardial fibrosis remains unclear." (PMID 41751765, 2026). "Myocardial fibrosis, mediated by excessive collagen deposition and influenced by fibroblast growth factor-2 (FGF-2) and transforming growth factor-beta (TGF-β), plays a pivotal role in the structural remodeling of hypertensive myocardium." (PMID 40362262, 2025). "In conclusion, this study provides evidence that Serpine1 may be a potential mechanism that enables CHIR99021 combined with FGF2 to improve myocardial fibrosis." (PMID 41751765, 2026). "Taken together, IL-1β functions as a factor downstream of NLRP3 inflammatory vesicles and participates in the process of myocardial fibrosis by promoting the production of factors such as TGF-β1 and activating FGF-2 to promote End-MT." (PMID 40881586, 2025). "Myocardial fibrosis was more severe in the AF group than in the control group, with increased interstitial cells, disordered myocardial arrangement, and higher expression of COL I, FGF-2, and α-SMA (p < 0.05)." (PMID 40989585, 2025). "Therefore, according to the results of this experiment, kidney‐derived TGF‐β1 and FGF2 were not involved in myocardial fibrosis in the CKD model." (PMID 36102251, 2022).
renal fibrosis (16 papers, 2020 to 2025). A final common manifestation of a wide variety of chronic kidney diseases characterized by glomerulosclerosis and tubulointerstitial fibrosis. "Inhibition of MAPK/ERK downregulates the expression of maladaptive tubular EGR1 and FGF2, improving renal fibrosis and renal function." (PMID 40827445, 2025). "Renal fibrosis was evaluated by the area occupied by collagen fibers in the renal glomeruli and by the immunoexpression of FGF-2." (PMID 37851784, 2023). "Livingston MJ and colleagues showed that fibroblast growth factor 2 (FGF2) production in tubular cells mediated renal fibrosis through the secretion of TGF-β1 to activate fibroblasts for renal fibrosis following acute kidney injury (AKI)." (PMID 37340199, 2023). "However, these macrophages produce a number of factors, such as TGF-β, PDGF, or FGF-2, which induce the formation of myofibroblasts and thus promote the development of renal fibrosis." (PMID 37383717, 2023). "Thus, Klotho is a critical negative regulator of canonical Wnt signaling and suppresses renal fibrosis in the obstructed kidney model by simultaneously suppressing multiple growth factor signaling pathways such as fibroblast growth factor-2 (FGF-2), Wnt, and TGF-β1." (PMID 34483931, 2021). "Although the direct causal relation between FGF2 and renal fibrosis has not been demonstrated yet, FGF2 is associated with TGFβ-induced proliferation of renal fibroblast, together with the induction of other profibrotic signaling molecules including Wnt4 and TNF-α." (PMID 32410988, 2020). "The correlation results of the present study indicated mutual positive correlations between the expression of TGF-β, FGF2, WNT, and β-catenin pointing to the interweaving of these profibrotic pathways to promote renal fibrosis." (PMID 40514411, 2025). "Macrophages contribute to renal fibrosis via several mechanisms: M2 macrophages produce profibrotic factors (e.g., TGF-β1, FGF-2, and PDGF), which promote myofibroblast proliferation and extracellular matrix overproduction." (PMID 36147851, 2022). "Most strikingly, in our study, we found that FATP2 can regulate the progression of renal fibrosis by mediating the secretion of several profibrotic cytokines (TGF-β, CTGF, PDGFB, FGF2), but the specific mechanism remained unclear." (PMID 33219209, 2020). "Fibroblast growth factor 2 (FGF2) and fibronectin produced after UUO enhance renal fibrosis." (PMID 37962467, 2024). "To investigate the potential mechanism for the downregulation of JLP during UUO induced renal fibrosis, we treated cultured HK-2 cells, in which JLP was abundantly expressed, with TNF-α, TGF-β1, and FGF-2, which are the key initiators of inflammatory and fibrotic lesions." (PMID 32504044, 2020).
sarcoma (16 papers, 2002 to 2025). A usually aggressive malignant neoplasm of the soft tissue or bone. "ISG15 and IF16 are directly linked together but through PCNA and then through CCND1 they connect indirectly to the common to all sarcomas’ major hubs FGF2 and IL-6." (PMID 34359782, 2021). "A STAT-independent involvement of activated TYK2 in fibroblast growth factor 2 (FGF-2) mediated escape from drug-induced death was reported for a sarcoma cell line." (PMID 31694222, 2019). "Methods: 99mTc-FGF-2 was tested in vitro and in vivo in mice bearing allografts of sarcoma cells." (PMID 38672507, 2024). "Compared to healthy controls, plasma FGF2 levels, in sarcoma patients, is reported to be elevated." (PMID 21733164, 2011). "FGF2 presence has also been confirmed in studies of sarcoma cell-lines." (PMID 21733164, 2011).
squamous cell carcinoma (16 papers, 2003 to 2025). A carcinoma arising from squamous epithelial cells. "FGF1 treatment increases the basal ECAR in breast cancer cell lines, while FGF2 treatment increases lactate production in murine adipocytes, rat Sertoli cells, and human squamous cell carcinoma cells." (PMID 39433211, 2025). "An upregulation in FGF-2 expression has previously been observed in benign myoepithelial cells when using a squamous cell carcinoma cell line, suggesting that the excessive release of FGF-2 favored malignant cell growth." (PMID 25435982, 2015). "The present study was designed to investigate in epidermoid carcinoma cells the potential role of FGF2 in DNA repair." (PMID 22732006, 2012). "As FGF2 cell signalling has been involved in DNA repair of normal epidermal stem cells, such a role was investigated in epidermoid carcinoma stem cells." (PMID 22732006, 2012). "Similarly, inhibition of the PI3K/mTOR pathway suppresses FGF-2-induced glucose uptake in squamous cell carcinoma cells." (PMID 39433211, 2025). "FGF2 was found to mediate DNA repair in epidermoid carcinoma cells." (PMID 22732006, 2012). "In a recent study, the same group of researchers noted that ED-71 inhibited the growth of squamous cell carcinoma (SCC) cells in vitro and in vivo by down-regulating the expression of HBp17/FGFBP-1, a factor that enhances angiogenesis as well as promotes tumour growth, and FGF-2." (PMID 37299554, 2023). "FGFBP1 was firstly found in human epidermoid carcinoma A431 cells, acting as a noncovalent carrier for FGF-1 or FGF-2." (PMID 31058187, 2019).
lung adenocarcinoma (15 papers, 2014 to 2026). A carcinoma that arises from the lung and is characterized by the presence of malignant glandular epithelial cells. "FGF2 was associated with the growth of lung adenocarcinoma and pancreatic ductal adenocarcinoma." (PMID 38273381, 2024). "Inhibition of FGF2 or FGFR1 in a pemetrexed-resistant lung adenocarcinoma cell line resulted in downregulation of vimentin and Slug level, reversed EMT cell morphology, and partially restored sensitivity to pemetrexed." (PMID 34830951, 2021). "Prifenidone and nintedanib reversed EMT-related chemoresistance induced by TGFβ and FGF2 in human lung adenocarcinoma cells." (PMID 34830951, 2021). "It has been reported that lncRNA LINC00115 might be a prognostic lncRNA in lung adenocarcinoma, and functions as a ceRNA by interacting with hsa-miR-7 to regulate FGF2." (PMID 33028275, 2020).
mesothelioma (15 papers, 2009 to 2024). A usually malignant and aggressive neoplasm of the mesothelium which is often associated with exposure to asbestos. "In line with this, it was shown that antiproliferative effects of the multikinase inhibitor sorafenib were most pronounced in tumor-initiating mesothelioma cells which expressed high levels of FGF2, leading to autocrine activation of FGFR1." (PMID 31527449, 2019). "Herein, the efficacy of this molecule was tested in models of mesothelioma, a tumor type shown to express high levels of FGF2 and FGFR1." (PMID 27223434, 2016). "This study also demonstrated that GSK3052230 is effective in inhibiting tumor growth of FGF2/FGFR1-overexpressing mesothelioma xenografts." (PMID 27223434, 2016). "Inhibition of FGF/FGFR downstream signaling by GSK3052230 was tested in NCI-H226 and MSTO-211H mesothelioma cells stimulated with either FGF2 or other growth factors known to activate receptor tyrosine kinases (RTKs)." (PMID 27223434, 2016). "In vitro co-culture and migration experiments using several human mesothelioma cell lines (MSTO-211, Y-MESO-14) and human embryonic lung fibroblast cell lines showed that mesothelioma cells secreted FGF-2 and PDGF-AA." (PMID 24978438, 2014). "The intracellular distribution of Alexa-labeled FGF-2 was restricted to the cytoplasm of mesothelioma STAV-AB cells up to 42 hours after seeding." (PMID 19802384, 2009). "When associated with sEVs, TGFβ induces the transcription of mRNAs similar but not identical to those induced by TGFβ in soluble form; particularly, mesothelioma-released sEVs stimulated a strong induction of FGF2 mRNA while TGF-β treatment modestly induced FGF2 expression." (PMID 32015297, 2020). "In addition, Fibroblast Growth Factor 2 (FGF2) is seen in most mesothelioma tissue specimens by immunohistochemistry (IHC) and leads to proliferation of fibroblast cell lines in vitro and migration to the malignancy in xenograft models in SCID mice." (PMID 31867277, 2019). "Similarly, FGF2 mRNA levels are highest in mesothelioma cell lines compared to all other cancer cell lines in the Cancer Cell Line Encyclopedia (CCLE), and FGFR1 expression is also high in these cells." (PMID 27223434, 2016). "In the mesothelioma cells we could detect a nuclear pool of syndecan-1 and FGF-2, whereas FGFR-1 remained exclusively perinuclear." (PMID 19802384, 2009). "Notably, high expression of FGF2 in mesothelioma correlates with poor prognosis." (PMID 39376629, 2024). "It is a concern that factors previously reported as being secreted by MPM cells, such as FGF2, HGF, PDGF-AA and VEGF validated poorly across patient-derived and commercial mesothelioma cell lines in our study." (PMID 37938546, 2023). "Our published findings in NSCLC, mesothelioma and ovarian MPE reveal a profound degree of polarization dominated by near nM concentrations of IL-6/sIL6Rα, IL-8, IL10, VEGF, FGF2 and CXCL10." (PMID 37063842, 2023). "Other angiogenesis-related factors, such as fibroblast growth factor-2 (FGF-2) and hepatocyte growth factor (HGF), are hyper-expressed in mesothelioma, at 50% and 85%, respectively." (PMID 29342862, 2018). "Taken together, this data suggests that FGF autocrine signaling based on FGF2 and/or FGFR1 overexpression is important for mesothelioma cell proliferation." (PMID 27223434, 2016). "Overexpression of FGF2 protein has been observed in primary mesothelioma tumor specimens, and both FGF2 and FGFR1 mRNA expression levels are high in mesothelioma compared to other tumor types in The Cancer Genome Atlas (TCGA) collection." (PMID 27223434, 2016). "The other cell line, NCI-H2052, is a mesothelioma cell with high levels of FGF2 that previously demonstrated a lack of sensitivity to FGF pathway inhibition." (PMID 27223434, 2016). "Furthermore, FGF2 leads to fibroblast production of hepatocyte growth factor (HGF) and platelet-derived growth factor A (PDGF-A) which can in turn stimulate the growth and migration of mesothelioma cell lines." (PMID 31867277, 2019).
mesothelioma (continued). "However, such transport of exogenous FGF-2 from the cell surface to the nucleus could not be verified in the mesothelioma cells." (PMID 19802384, 2009).
nasopharyngeal carcinoma (15 papers, 2008 to 2025). A carcinoma arising from the nasopharyngeal epithelium. "In nasopharyngeal cancer survivors, elevated FGF2 levels in tissues activate CXCL14, promoting M2 macrophage polarization and tumor metastasis." (PMID 39436561, 2024). "The authors identified nasopharyngeal carcinoma (NPC) as a highly FGF2-expressing tumor type with predominant macrophage infiltration." (PMID 39086395, 2024). "Fibroblast growth factor 2 (FGF2), secreted by nasopharyngeal cancer cells, promotes pericyte proliferation." (PMID 37686288, 2023). "Here, we report that an elevation of FGF-2 signaling in samples from patients with nasopharyngeal carcinoma (NPC) and xenograft mouse models promoted NPC metastasis." (PMID 35439170, 2022). "In nasopharyngeal carcinoma, FGF2 signaling modulates pericyte-macrophage crosstalk and metastasis." (PMID 38745238, 2024). "Notably, FGF2 is a direct transcriptional target of miR-16 in human nasopharyngeal carcinoma cells, indicating the additional repression of FGF2 signaling by this miRNA." (PMID 37685951, 2023). "Additionally, miR-16 over-expression significantly reduced FGF2 mRNA expression and inhibited nasopharyngeal carcinoma cell proliferation and migration." (PMID 31262262, 2019). "Notably, FGF2 is a direct transcriptional target of miR-16 in human nasopharyngeal carcinoma cells, indicating additional repression of FGF2 signaling by this miRNA." (PMID 30081513, 2018).
type 2 diabetes (15 papers, 2013 to 2025). "The paracrine effect of USCs or USCs-FGF2 induced improvement of erectile function in type 2 diabetic rats by recruiting resident cells and increasing the endothelial expression and contents of smooth muscle." (PMID 24663037, 2014). "The aim of this study was to determine the possibility of improving erectile dysfunction using cell therapy with either human urine-derived stem cells (USCs) or USCs genetically-modified with FGF2 in a type 2 diabetic rat model." (PMID 24663037, 2014). "In our study, the levels of FGF-2, FGF-19, FGF-22, and FGF-23 were measured in patients with type 1 and type 2 diabetes and compared with healthy controls." (PMID 40943671, 2025). "The study aimed to analyze and compare the concentrations of selected fibroblast growth factors, FGF-2, FGF-19, FGF-22, and FGF-23, in the plasma of patients with type 1 and type 2 diabetes with those of the control group." (PMID 40943671, 2025). "Overall, these results indicate that both age and BMI are consistently associated with reduced concentrations of FGF-19 and FGF-22, particularly in patients with type 2 diabetes, whereas FGF-2 and FGF-23 showed no consistent correlations with either parameter." (PMID 40943671, 2025).